PRL (prolactin)
Diseases named in the same sentence as PRL in open-access papers (continued):
Sharing a sentence is not in itself a finding about the gene and the disease.
tumor (continued). "While this treatment effectively reduces prolactin levels and tumor size in the majority of patients, approximately 20% exhibit resistance to BRC." (PMID 40444042, 2025). "A small sample study showed that preoperative treatment with cabergoline improved biochemical control in acromegaly patients, with tumor volume changes mainly observed in GH/prolactin co-secreting tumors, and less frequently in tumors that solely secrete GH." (PMID 41550875, 2025). "Our findings show that the discriminative ability of tumor size metrics in predicting clinical response, defined as PRL reduction, varies over time." (PMID 40995599, 2025). "During this intricate process, progesterone also mediates prolactin (PRL) secretion, which has been shown in studies to possess anti-apoptotic effects and support tumor growth in certain types." (PMID 41278208, 2025). "Our case fits well within these observations: a 5 cm invasive tumor that produced a massive “supraphysiological” PRL level (>50,000 ng/mL)." (PMID 40599499, 2025). "Post-radiation, his tumor size and prolactin levels (642 ng/mL or 13659.57 mIU/L) remained stable on lower doses of cabergoline (1 mg per week)." (PMID 41013821, 2025). "Histological and immunohistochemical analyses, including prolactin and transcription factor staining, are essential for accurate tumor classification." (PMID 41140514, 2025). "Once again, PRL-secreting PitNETs showed particular proliferative behavior, with about 20% of cases presenting a high proliferative index (61 to 100% out of total tumor cells)." (PMID 41614857, 2025). "The greatest efficacy is reported to occur within the first six months of treatment initiation, and normalization of prolactin and tumour volume reduction exceeding 25% within the first 3 months of treatment is predictive of long-term response." (PMID 40004619, 2025). "Our data also point to enrichment in adipocytokine and prolactin signaling pathways, highlighting the potential role of the tumor microbiome in inflammation and metabolism, with implications for T-cell and B cell-specific immunotherapy in clinical settings." (PMID 40013793, 2025). "DA resistance is defined as the failure to normalize PRL levels and to achieve at least 50% tumor size reduction on the maximally tolerated doses of DA, after at least 6 months of therapy." (PMID 40995599, 2025). "Following surgery, he was maintained on cabergoline 1.5 mg twice weekly, but despite treatment, the tumor continued to grow, and prolactin levels remained elevated at 241 ng/mL (5127.66 mIU/L)." (PMID 41013821, 2025). "We reviewed age at diagnosis, tumor size, initial prolactin level, medical treatment, and reason for surgery." (PMID 41156214, 2025). "Regarding PRL secreting PitNETs, we observed that all cases had a high number of proliferating endothelial cells lining the tumor vasculature." (PMID 41614857, 2025). "Despite the high-dose therapy, only a partial reduction in tumour size and prolactin levels was achieved." (PMID 41322860, 2025). "During the postpartum follow-up, the patient experienced a resumption of menstrual cycles, normalization of prolactin levels, and a reduction in tumor size." (PMID 39816925, 2025). "Medical treatment should be maintained until the normalization of PRL concentrations and reduction of tumor size." (PMID 39949381, 2025). "This review evaluates the interplay between melatonin and PRL signaling in mammary oncogenesis, with particular emphasis on melatonin's potential to modulate PRL-driven tumor progression through endocrine and paracrine mechanisms." (PMID 41370498, 2025). "Dopamine agonists effectively inhibit prolactin secretion in 90% of patients with prolactinoma and lead to substantial tumor shrinkage due to reduction of the lactotrophs’ cell size." (PMID 40327154, 2025).
tumor (continued). "Dopamine agonist therapy is the recommended medical therapy for patients with prolactinoma, as it is effective at decreasing prolactin levels and decreasing tumor size, although hormone replacement therapy can be considered in certain clinical scenarios." (PMID 40321172, 2025). "In this context, other studies highlighted that the nadir prolactin level during treatment was the most important predictor of tumor shrinkage." (PMID 40995599, 2025). "MRI revealed further tumor progression (5 × 3 cm) with invasion into the cavernous sinus and tracking along the trigeminal nerve and prolactin levels were > 4700 ng/mL (> 100000 mIU/L)." (PMID 41013821, 2025). "Medical treatment with dopamine agonists (DA) is the therapy of choice for PRL with humoral response, defined as normoprolactinemia in 68% of cases, tumor shrinkage in 62% of cases and relieving infertility or other symptoms in 53%, respectively." (PMID 38645431, 2024). "Baseline PRL concentrations before treatment correlate with tumor size, and thus due to the larger diameter of tumors in men, PRL levels in this group of patients are significantly higher than in women." (PMID 38370355, 2024). "Dopamine agonists (DAs) like cabergoline and bromocriptine are the first-line treatment for prolactin-secreting tumors, with cabergoline being over 90% effective in normalizing prolactin levels and decreasing tumor size." (PMID 39677352, 2024). "In paired analyses comparing clinical data from baseline to follow-up, we noted a significant reduction in tumor size, volume, and prolactin levels, as expected." (PMID 38645431, 2024). "The primary treatment goal for most patients with prolactinomas is to restore normal prolactin secretion and reduce tumor size." (PMID 38654814, 2024). "Transsphenoidal surgery can correct the hyperprolactinemic state by reducing the tumor mass, however, occasionally an excessive decrease in prolactin levels below the normal ranges has been observed." (PMID 39080760, 2024). "After menopause and discontinuation of dopamine agonists, we recommend follow-up with clinical evaluation and measurement of prolactin levels every 6 months in the first year and pituitary MRI at 12 months or earlier if symptoms of tumor mass effect develop." (PMID 38578473, 2024). "DAs efficacy in reducing prolactin secretion resulting in normalized hormone levels in about 90% and inducing tumor shrinkage in 70–90% has positioned them as the cornerstone of medical treatment for prolactinoma patients." (PMID 39085706, 2024). "Specifically, 9 cases of GH-secreting tumours (one co-secreting prolactin), all macro-tumours, have been reported in patients younger than 30 years." (PMID 37891382, 2024). "CNNM4 (cyclin and CBS domain divalent metal cation transport mediator 4), a member of the CNNM (Cyclin M) family, binds to PRL (prolactin) to regulate magnesium homeostasis and influence tumor cell proliferation." (PMID 39691602, 2024). "It has been reported that higher Ki-67 correlates positively with tumor size, PRL levels and DA resistance; thus macroPRLomas and invasive tumors generally present significantly higher Ki-67 than microPRLomas." (PMID 38370355, 2024). "While prolactin is well recognized for its roles in lactation and tumor progression, its involvement in iron homeostasis has remained elusive." (PMID 39201626, 2024). "Patient’s tumor shrank, and the blood levels of PRL decreased and remained stable for one year.EVE combined with CAB had an additive effect in suppressing PRL secretion but not on PAs cell proliferation." (PMID 39736867, 2024). "This BP-lowering effect was significantly associated with several variables, including age, sex, disease duration, tumor size, invasion, resistance to dopamine agonists (DAs), recurrence, and preoperative PRL levels." (PMID 38398117, 2024). "The risk of symptomatic growth of prolactinomas during pregnancy is dependent on the tumor's size, duration of previous treatments, and prolactin levels." (PMID 38578473, 2024).
tumor (continued). "The tumor was nonfunctioning in 23 patients, while one had an adrenocorticotropic hormone-secreting tumor and one a prolactin-secreting tumor." (PMID 38707178, 2024). "Our patient was started on cabergoline with eventual normalization of prolactin levels as well as tumor size regression from 8 mm to 4 mm on follow-up MRI 18 months after presentation." (PMID 39050327, 2024). "Prolactin promotes proliferation and migration of cancer cells, enhances tumor stemness, and drives tumor metastasis." (PMID 39201626, 2024). "In the majority of patients, DAs effectively lower serum prolactin levels and reduce tumor size, thereby alleviating clinical symptoms." (PMID 39684198, 2024). "PRL was 292.3 ng/mL, and MRI of the head revealed a tumor-like lesion with a cystic portion 20 mm in the greatest diameter in the sella turcica." (PMID 38516477, 2024). "The first-line pharmacological treatment for prolactinoma includes dopamine agonists (DAs), such as bromocriptine or cabergoline, which aim to suppress excessive PRL secretion and reduce tumor size using the minimum effective dose." (PMID 38572480, 2024). "Prolactinoma treatment aims for normalization of prolactin levels and gonadal function, with tumor shrinkage." (PMID 39292628, 2024). "Prolactinoma patients require the use of DAs to suppress PRL synthesis and secretion, control PRL levels, and prevent tumor recurrence or further growth." (PMID 38572480, 2024). "For the treatment of symptomatic prolactinoma, Endocrine Society guidelines generally recommend initial treatment with dopamine agonists to lower prolactin levels and decrease tumor size." (PMID 39050327, 2024). "Both groups presented similar initial tumor volumes (1.9cm3 vs. 1.5cm3, p = 0.59) and equal preoperative prolactin levels (PRL) (199.7 μg/l vs. 191.0 μg/l, p = 0.44)." (PMID 39085706, 2024). "This BP-lowering effect was more prominent with age, sex, tumor size, invasion, resistance to DAs, recurrence, and preoperative PRL levels." (PMID 38398117, 2024). "Treatment outcomes were evaluated based on prolactin normalization, tumor shrinkage, and cabergoline dosage." (PMID 38645431, 2024). "In our analysis, we observed a correlation between increased BMI and tumor size, volume, or prolactin levels, as well as rising HbA1c levels in relation to tumor size and prolactin levels at baseline." (PMID 38645431, 2024). "The combined effects of tumor mass and excessive prolactin secretion often lead to clinical symptoms such as headaches, visual impairment, amenorrhea, galactorrhea, and reduced sexual function." (PMID 39684198, 2024). "The BP-lowering effect was significantly associated with several variables, including age, sex, disease duration, tumor size, invasion, dopamine agonists (DAs)-resistance, recurrence, and preoperative PRL levels." (PMID 38398117, 2024). "The mean prolactin value at the initial presentation was 2734.6 ng/mL, and the mean maximum tumor diameter was 40.4 mm." (PMID 38516477, 2024). "Eight patients responded to cabergoline treatment with normalization of prolactin levels and tumor shrinkage." (PMID 38516477, 2024). "After menopause and discontinuation of DA, we suggest follow-up with clinical evaluation and PRL dosage every six months in the first year and pituitary MRI at 12 months or earlier if there are symptoms of tumor mass effect." (PMID 38765515, 2024). "We also found that the cells expressing both GH1 and PRL had different expression patterns between the normal and tumor samples." (PMID 38167466, 2024). "Transmission electron microscopy experiments confirmed the existence of both somatotropin and prolactin particles in the same tumor cells." (PMID 38167466, 2024). "The risk of symptomatic growth of prolactinomas during pregnancy is related to the size of the tumor, duration of previous treatment, and higher prolactin levels." (PMID 38578473, 2024).
tumor (continued). "Follow-up data indicated decreases in tumor size, tumor volume, prolactin levels, and LDL-cholesterol, alongside increases in fT4 and sex hormones levels." (PMID 38645431, 2024). "In patients with macroprolactinomas, dopamine agonist therapy has been demonstrated to induce tumour shrinkage in 50–90% of cases, and normalisation of serum prolactin levels in 60–95% of cases." (PMID 39039214, 2024). "For every 1 cubic centimeter increase in preoperative tumor volume, the serum PRL levels increased by 101.31 μg/L." (PMID 38572480, 2024). "To better understand this relationship, we consulted previous literature and discovered several studies supporting prolactin’s potential role in promoting tumor recurrence." (PMID 39221033, 2024). "This study revealed that prolactin (PRL) levels in patients with prolactinoma are correlated with tumor size." (PMID 38572480, 2024). "The authors of this article compared tumor and normal cells and found that in normal tissues, many cells coexpress GH1 and PRL, while most tumor cells only express one." (PMID 39114291, 2024). "The patient had a PRL of 4914 ng/mL, and an MRI scan of the head showed a tumor in the sella turcica, with a maximum diameter of 25 mm." (PMID 38516477, 2024). "In clinical practice, we observed that some prolactinoma patients receiving bromocriptine (BRC) treatment fail to achieve normalized serum prolactin levels, with tumor size reductions remaining below 30%, indicating resistance to BRC therapy." (PMID 39684198, 2024). "At the time of diagnosis, the mean PRL level was 377.55 ± 265.42 ng/ml and tumor size—10.10 ± 7.0 mm." (PMID 38375408, 2024). "The classification also includes a new subtype of PitNET responsible for the secretion of TSH, GH, and PRL: the mature plurihormonal Pit-1 lineage tumor, composed of monomorphous cells." (PMID 38248047, 2024). "Main factors implicated in testosterone recovery in these patients include small tumor size, high baseline testosterone levels, and an early and robust prolactin decrease following the administration of dopaminergic agents." (PMID 39109291, 2024). "In summary, inhibiting the oncogenic miRNAs and ectopic expression of tumor-suppressive miRNAs can decrease prolactin secretion, reduce tumor invasion and migration, enhance dopamine agonist efficacy, and inhibit prolactinoma development." (PMID 39702128, 2024). "PRL-induced Stat5 activation is associated to high-grade prostate tumors and aggressiveness, and PRLR inhibition reduced tumor burden." (PMID 37208719, 2023). "The invasiveness of tumor and levels of blood prolactin are independent factors for LTLs before surgery, whereas GH and IGF-1 levels are not." (PMID 37886642, 2023). "Of 79 prolactinoma cases, 8 patients had GP with a median age of 38 years (range 20–53), 75% (6/8) were male, with a median largest tumor dimension of 6 cm (range 4.6–7.7), and a median prolactin level of 2,500 μg/L (range 100–>13,000)." (PMID 37143698, 2023). "DA bind to dopamine type 2 receptors (D2R) in prolactinomas resulting in inhibition of PRL secretion as well as reduction of tumor size." (PMID 36927797, 2023). "The decrease in PRL and tumor size after the first year of treatment predicted the long-term combined response." (PMID 37403202, 2023). "Dopamine agonists (DA) are the first-line treatment for prolactinomas and lead to inhibition of PRL production and secretion, improved gonadal function, and reduced tumor size." (PMID 37403202, 2023). "This combination resulted in a decline in prolactin levels and decreased tumor sizes in all patients." (PMID 36835974, 2023). "In our cohort, PRL normalized in 55% of the patients, and a tumor response was seen in 69% of the patients." (PMID 37403202, 2023). "Our data demonstrates relatively high relief rates for serum prolactin, growth hormone, and cortisol after microscopic tumor resection (77.4%, 71.8%, and 66.7% respectively)." (PMID 37964947, 2023).
tumor (continued). "The most commonly used definition is failure to normalize PRL and/or reduce tumor volume by at least 50% using conventionally maximum or maximally tolerated doses of DA (for example, BRC 7.5 mg/day or CAB 2 mg/week)." (PMID 36927797, 2023). "Unlike in the AIPvar group, the DA-resistant group had a sub-set of patients that are characterized by very high prolactin and large tumor size." (PMID 37711900, 2023). "The pooled proportions of patients with prolactin concentration normalization and tumor reduction (>50%) under CV treatment were 69% and 20%, respectively, with 95% confidence intervals of 61%-76% and 15%-28%, respectively." (PMID 36761195, 2023). "As for PRLR, prolactin (PRL) has been traditionally associated with lactation and fertility, but recently it has been reported to promote tumor cell proliferation, angiogenesis, and chemoresistance." (PMID 36836422, 2023). "The initial use of bromocriptine later shifted to cabergoline, which has been effective in regulating prolactin levels in up to 85% of patients and reducing tumor size in about 80% of cases." (PMID 38275385, 2023). "Other authors have also described a poorer response to medical therapy and a higher risk for recurrence in tumors with positive staining for GH and PRL than in single-staining PitNETs despite similar tumor size." (PMID 37762304, 2023). "For cystic prolactinomas, tumor size and preoperative PRL levels were independent predictors of early postoperative remission." (PMID 37143054, 2023). "In 2 patients achieving PRL normalization and complete tumor regression after a total treatment period of 3 and 21 years, respectively, DA (BRC and CAB, respectively) was discontinued." (PMID 37403202, 2023). "The authors concluded that the addition of an aromatase inhibitor allowed for the continued use of testosterone as it prevented the testosterone-induced prolactin increase and potential tumor enlargement." (PMID 36835974, 2023). "The overall treatment goals for prolactinomas are normalized PRL levels; recovery of gonadal, pituitary, and visual functions; and reduction of tumor size." (PMID 37403202, 2023). "The patient received cabergoline and tamoxifen combination therapy and showed normalization of prolactin levels with a resolution of the residual tumor." (PMID 36950000, 2023). "Invasiveness of the tumor and the level of blood prolactin are independent factors for LTLs before surgery, whereas the GH and IGF-1 levels are not." (PMID 37886642, 2023). "As an additional measure, based on evidence from in vivo and in vitro studies and case reports, anti-estrogens have been proposed as an intervention with the potential to reduce prolactin levels and tumor size." (PMID 36950000, 2023). "As for PRL-PitNETs, we considered a tumor responsive when the treatment reduced cell proliferation by at least 15%." (PMID 37370829, 2023). "Through multivariate stepwise logistic regression, the present study found that tumor size and preoperative PRL ≥ 200 ng/ml were independent factors affecting postoperative remission (p = 0.016, p = 0.017, respectively)." (PMID 37143054, 2023). "Traditionally, dopamine agonists have been the primary treatment, with cabergoline effectively normalizing prolactin levels in most patients and inducing tumor shrinkage in many." (PMID 38275385, 2023). "Response to medical treatment is considered satisfactory when there is normalization of prolactin levels together with a 50% reduction in tumor size within approximately the first 6 months of treatment." (PMID 37908013, 2023). "Normalized PRL was achieved in 55%, significant tumor reduction in 69%, and combined response (normalized PRL and significant tumor reduction) in 43%." (PMID 37403202, 2023). "In our patients treated with DA monotherapy, PRL normalized in 62% of the patients, and there was a significant tumor response in 67%." (PMID 37403202, 2023).